SKIC2 (SKI2 subunit of superkiller complex)
Description:
Helicase component of the SKI complex, a multiprotein complex that assists the RNA-degrading exosome during the mRNA decay and quality-control pathways. The SKI complex catalyzes mRNA extraction from 80S ribosomal complexes in the 3'-5' direction and channels mRNA to the cytosolic exosome for degradation. SKI-mediated extraction of mRNA from stalled ribosomes allow binding of the Pelota-HBS1L complex and subsequent ribosome disassembly by ABCE1 for ribosome recycling. In the nucleus, the SKI complex associates with transcriptionally active genes in a manner dependent on PAF1 complex (PAF1C). May play a role in the non-stop mRNA decay pathway (NSD), which specifically targets and degrades mRNAs that lack a proper stop codon.
Synonyms: Ski2; HLP; DDX13; SKI2W; SKIV2; SKIV2L; 170A; SKIV2L1; THES2
Tractability: PROTAC: ubiquitination databases record sites on it.
Gene: Protein-coding gene on chromosome 6 (31,959,116 to 31,969,852, forward strand). Ensembl gene ENSG00000204351.
Subcellular location: Nucleus; Cytoplasm
Subcellular location (Human Protein Atlas): Nuclear bodies; Nucleoplasm; Cytosol; Mitotic spindle
Pathways (Reactome):
Metabolism of RNA: mRNA decay by 3' to 5' exoribonuclease
Metabolism of proteins: Association of TriC/CCT with target proteins during biosynthesis
Gene Ontology:
Molecular function: 3'-5' RNA helicase activity; ATP hydrolysis activity; protein binding; RNA helicase activity; ATP binding; nucleic acid binding; RNA binding
Biological process: nuclear-transcribed mRNA catabolic process; nuclear-transcribed mRNA catabolic process, 3'-5' exonucleolytic nonsense-mediated decay; nuclear-transcribed mRNA catabolic process, non-stop decay; rescue of stalled ribosome; mRNA catabolic process; RNA catabolic process
Cellular component: nucleus; Ski complex; cytoplasm; cytosol
Genetic constraint (gnomAD): Loss-of-function variants: 104 observed, 141.1 expected, observed/expected ratio (o/e) 0.74, 90% interval 0.63 to 0.87. The synonymous counts are far from expectation, so gnomAD's model fits this gene poorly and the ratio says little. Missense variants: 1,401 observed, 1,664.6 expected, observed/expected ratio (o/e) 0.84, 90% interval 0.81 to 0.88. Synonymous variants: 528 observed, 650.64 expected, observed/expected ratio (o/e) 0.81, 90% interval 0.75 to 0.87.
Gene-disease validity (ClinGen):
ClinGen rates the evidence that SKIC2 causes each of these diseases.
trichohepatoenteric syndrome 2 (autosomal recessive): Definitive.
Homologues: Orthologues: chimpanzee SKIC2 (99% identical), macaque SKIC2 (98% identical), rabbit SKIC2 (95% identical), rat Skic2 (93% identical), mouse Skic2 (93% identical), guinea pig SKIC2 (92% identical), pig SKIC2 (91% identical), zebrafish skic2 (61% identical), tropical clawed frog skic2 (58% identical), Drosophila melanogaster tst (42% identical), Caenorhabditis elegans skih-2 (40% identical). Paralogues in human: MTREX (30% identical), POLQ (17% identical), ASCC3 (14% identical), DDX60 (14% identical), DDX60L (14% identical), HELQ (13% identical), HFM1 (13% identical), SNRNP200 (13% identical).
Diseases named in the same sentence as SKIC2 in open-access papers:
SKIC2 is named in the same sentence as 61 diseases in open-access papers, as found by Europe PMC text mining. Sharing a sentence is not in itself a finding about the gene and the disease. The quoted sentences say what the papers report.
trichohepatoenteric syndrome (14 papers, 2018 to 2024). A severe congenital enteropathy manifesting as intractable diarrhea in the first month of life with failure to thrive and associated with facial dysmorphism, hair abnormalities, and, in some cases, immune disorders and intrauterine growth restriction. "Trichohepatoenteric syndrome (THES) is a genetic disorder caused by autosomal recessive mutations in the SKIC2 or SKIC3 genes that impact the SKI complex, which is essential for RNA surveillance." (PMID 38987716, 2024).
liver disease (4 papers, 2013 to 2025). "Tricho-hepato-enteric syndrome (THES), a rare autosomal recessive disorder caused by variants in the SKIC3 or SKIC2 gene, is characterized by intractable diarrhea, woolly hair, growth restriction and liver disease." (PMID 40675981, 2025). "In addition, she developed portal hypertension and varices, which are considered uncommon in patients with SKIC3 mutations and were described in one patient with SKIC2 mutations." (PMID 38987716, 2024).
SKIC2 also shares sentences with these, for which no sentence is quoted: viral infection (7 papers); infection (6); multiple sclerosis (6); autoimmune disease (5); cancer (5); Autoimmunity (3); Immunodeficiency (3); ectodermal dysplasia (2); genetic disorder (2); hemophagocytic syndrome (2); lymphoma (2); abortion (1); bronchiolitis (1); cholestasis (1); chronic inflammatory demyelinating polyradiculoneuropathy (1); Cirrhosis (1); coronary artery disease (1); COVID-19 (1); Creutzfeldt-Jakob disease (1); Crohn disease (1); depression (1); Diarrhea (1); endometrial carcinoma (1); gout (1); HCMV infection (1); heart failure (1); Henoch-Schonlein purpura (1); Hypertension (1); hypotrichosis (1); inflammatory bowel disease (1).
A further 29 diseases each share a sentence with SKIC2 in 1 paper.